PTGER4 (prostaglandin E receptor 4)
Diseases named in the same sentence as PTGER4 in open-access papers (continued):
Sharing a sentence is not in itself a finding about the gene and the disease.
ankylosing spondylitis (10 papers, 2013 to 2025). An autoimmune chronic inflammatory disorder characterized by inflammation in the vertebral joints of the spine and sacroiliac joints. "According to reports, ankylosing spondylitis (AS) shows a strong association with genetic variations in the PTGER4 gene." (PMID 38415452, 2024). "We aim to examine the influence of JARID1A, JMY, and PTGER4 polymorphisms on the susceptibility to and the severity of ankylosing spondylitis in Chinese ethnic majority Han population." (PMID 24069348, 2013). "Furthermore, we pin-pointed another suggestive QTL on ECA21, near the PTGER4 gene, associated with human ankylosing spondylitis, for shape differences in the back and pelvis (roach back vs sway back)." (PMID 37268682, 2023). "Interestingly, polymorphisms of the human EP4 receptor gene PTGER4 have been identified as risk alleles for ankylosing spondylitis (AS), and its expression by Th17 cells is associated with higher disease activity in AS, but not RA and PsA." (PMID 34303373, 2021). "An important role for EP4 receptor could be suggested since polymorphisms in PTGER4 loci are associated with increased PTGER4 gene expression in synovial biopsy samples from patients with spondyloarthritis, and PTGER4 is a susceptibility gene for ankylosing spondylitis and RA." (PMID 32962984, 2020). "Finally, 28 top shared SNPs near PTGER4 (5p13.1) are associated with CD, multiple sclerosis, and self-reported allergy, with other SNPs in the region being associated with immune-related traits (UC, psoriasis, selective IgA deficiency, ankylosing spondylitis, and blood protein levels)." (PMID 29309429, 2018).
bladder cancer (10 papers, 2018 to 2024). "Next, we examined the mutations in these genes in bladder cancer and found that the mutation frequency of PTGER4 was the highest, reaching 9%, with amplification mutations as the main mutation; it was followed by RUNX1, IL7, and CIITA, with mutation frequencies of 6, 5, and 5%, respectively." (PMID 32655621, 2020). "Therefore, the role of PTGER4 in bladder cancer needs further investigation." (PMID 34692520, 2021).
ovarian carcinoma (10 papers, 2007 to 2025). A malignant neoplasm originating from the surface ovarian epithelium. "PTGER2 and PTGER4 have been most studied in ovarian cancer and implicated in promoting growth and pro-tumorigenic cytokine production." (PMID 25972361, 2015). "This study demonstrates that PDP improves the anti-migratory activity of a prostaglandin E receptor 4 antagonist in ovarian cancer cells." (PMID 34771424, 2021). "Photodynamic priming and antagonism of the prostaglandin E receptor 4 independently attenuated OVCAR-5 ovarian cancer cell migration in a gap closure model, though their combination induced the most significant reductions." (PMID 34771424, 2021).
psoriasis (10 papers, 2018 to 2025). An autoimmune condition characterized by red, well-delineated plaques with silvery scales that are usually on the extensor surfaces and scalp. "Our CHi-C data showed interactions (CHiCAGO score ≥ 5) between multiple psoriasis-associated fragments and PTGER4 over approximately 300 kb to the other end of the TAD, a finding that was robust in all cell types." (PMID 32366252, 2020). "At the 5p13.1 locus, the psoriasis SNPs are similarly intergenic, but the nearest gene PTGER4 has been shown to be a strong candidate for other autoimmune diseases at this locus." (PMID 32366252, 2020).
melanoma (9 papers, 2013 to 2024). A malignant, usually aggressive tumor composed of atypical, neoplastic melanocytes. "PTGER4 can stimulate bone resorption, and the PTGER4 antagonist suppresses osteolysis due to bone metastasis of mouse malignant melanoma cells." (PMID 38445456, 2024).
atherosclerosis (8 papers, 2014 to 2025). A disease characterized by the build-up of fatty material and calcium deposition in the arterial wall resulting in partial or complete occlusion of the arterial lumen. "In myeloid cells, a key cell type in atherosclerosis, PGE2 acts predominately through its Prostaglandin E Receptor 4 (EP4; Ptger4) to modulate inflammation." (PMID 27351842, 2016).
endometriosis (8 papers, 2015 to 2025). The growth of functional endometrial tissue in anatomic sites outside the uterine body. "Taken together, the causal associations of EPHB4 and PTGER4 with endometriosis received the most robust support." (PMID 41353125, 2025). "The causal associations of PTGER4 and EPHB4 with endometriosis exhibited the highest robustness." (PMID 41353125, 2025). "Other evidence may strengthen our findings as PTGER2 and PTGER4 were found to play a key role in endometriosis development, and their inhibition leads to poor prognosis." (PMID 41583321, 2025). "As a consequence, the therapeutic inhibition of COX-2, PGE2, and/or their receptors—prostaglandin E receptor 2 (PTGER2) and prostaglandin E receptor 4 (PTGER4)—decreases the survival and invasive ability of endometriosis cells." (PMID 37447296, 2023). "To further investigate the potential pathogenic mechanisms of PTGER4 and EPHB4 in endometriosis and to elucidate the targets of relevant non-steroidal anti-inflammatory drugs (NSAIDs), we performed a functional enrichment analysis on these core genes based on drug-target interactions." (PMID 41353125, 2025).
multiple sclerosis (8 papers, 2012 to 2021). A progressive autoimmune disorder affecting the central nervous system resulting in demyelination. "Numerous GWAS studies have suggested that polymorphisms in the 5p13.1 regulatory regions near PTGER4 (e.g. rs9292777, rs7725052, rs77145747, rs6896969 and rs4613763) were significantly associated with PTGER4 gene expression and the susceptibility of MS." (PMID 30381825, 2019). "Because prostaglandin E receptor 4 is involved in the pathophysiology of experimental autoimmune encephalomyelitis (EAE), an animal model of human multiple sclerosis (MS), we assessed the beneficial effect of AA3 in EAE mice." (PMID 28759648, 2017). "CXCR4 and PTGER4 were higher expressed in subcortical white matter compared to cortical grey matter microglia, and ADGRG1 was downregulated in microglia obtained from normal-appearing white and grey matter tissue of multiple sclerosis (MS) brains." (PMID 34054860, 2021).
pancreatic cancer (8 papers, 2011 to 2024). "Knockout (KO) of Ptges (the gene encoding the PGE2 synthesis enzyme mPGES-1) or the EP4 receptor gene (Ptger4) in KPCY (KrasG12DP53R172HYfpCrePdx) pancreatic tumor cells abolished growth of implanted tumors in a T cell–dependent manner." (PMID 39298269, 2024).
autoimmune disease (7 papers, 2012 to 2020). A disorder resulting from loss of function or tissue destruction of an organ or multiple organs, arising from humoral or cellular immune responses of the individual to their own tissue constituents. "In addition, the association might be further enhanced by epigenetic factors, as shown by epigenetic fine-mapping of autoimmune disease-associated enhancer RNA (eRNA) located near the PTGER4 gene." (PMID 31253169, 2019). "So, combining genetic and molecular data, PTGER4 pharmacological modulation appears as an excellent strategy for new drug development in human autoimmune diseases including MS." (PMID 22570697, 2012).
ulcerative colitis (7 papers, 2018 to 2025). An inflammatory bowel disease involving the mucosal surface of the large intestine and rectum. "Studies have found that PTGER4 gene locus are associated with various diseases, such as rs4613763 being associated with ulcerative colitis." (PMID 37670284, 2023).
inflammatory bowel disease (6 papers, 2012 to 2022). A spectrum of small and large bowel inflammatory diseases of unknown etiology. "PTGER4 encodes the prostaglandin receptor EP4 which is a strong candidate susceptibility gene for inflammatory bowel diseases." (PMID 22570697, 2012).
diabetes (5 papers, 2015 to 2025). "Because the PGE2 receptor EP4 (Ptger4) has been implicated in inflammatory activation associated with diabetes, we generated a mouse model of myeloid cell-targeted EP4-deficiency by taking advantage of the EP4-floxed mouse and Lyz2-CreTg mice, which express Cre recombinase in myeloid cells." (PMID 27351842, 2016).
Ureteral obstruction (5 papers, 2012 to 2024). Obstruction of the flow of urine through the ureter. "Prostaglandins play an important role in ureteral obstruction, but the detailed expression profiles of the prostaglandin receptors (PTGER1, PTGER2, PTGER3, PTGER4, PTGFR) remain unknown in the different parts of the human ureter." (PMID 23227994, 2012).
Allergy (4 papers, 2017 to 2025). An allergy is an immune response or reaction to substances that are usually not harmful. "PTGER4 gene polymorphisms (rs7720838 and rs1494558) were associated with allergy and asthma, while rs4613763 was suggested as a psoriasis susceptible locus." (PMID 30381825, 2019). "For ten of these reQTL genes the eQTL was absent under baseline condition (pbaseline > 0.01), including reQTL genes such as APOL2 potentially associated with glomerulosclerosis, PTGER4 with allergy, and PIP4K2A with acute lymphoblastic leukemia." (PMID 28814792, 2017). "Furthermore, epigenetic changes in the PTGER4 gene enhancer in Th17 cells were also found to be associated with human autoimmune diseases such as MS, CD and allergy." (PMID 30381825, 2019).
endometrial cancer (4 papers, 2011 to 2020). Primary or metastatic malignant neoplasm involving the endometrium (mucous membrane that lines the endometrial cavity). "There was an increase in EP3 (PTGER3) and EP4 (PTGER4) receptor gene expression in type I and type II endometrial cancers which could lead to an increase in local PGE2-EP3/EP4 mediated signaling." (PMID 32982722, 2020). "However, of particular significance to this study was the observation of a significant increase in expression of PTGER4 in endometrial cancer compared with normal endometrium across the menstrual cycle." (PMID 21589857, 2011).
hepatocellular carcinoma (4 papers, 2020 to 2024). A malignant tumor that arises from hepatocytes. "Here, we identified a critical tumor-promoting and prometastatic role for chemotherapy-generated pancreatic and hepatocellular cancer cell debris, which triggers a storm of proinflammatory eicosanoid-driven cytokines via the upregulation of Ephx2 and Ptger4." (PMID 34607951, 2021).
type 2 diabetes (4 papers, 2013 to 2025). "Both type 2 diabetes (two at SND1–PAX4 locus and one at GAST locus) and GC (EFNA1, PTGER4 and PSCA loci) shared three significant variants after Bonferroni’s correction (P < 8.6 × 10−6) with PUD or its subtypes." (PMID 38036781, 2023).
dilated cardiomyopathy (3 papers, 2018 to 2022). Cardiomyopathy which is characterized by dilation and contractile dysfunction of the left and right ventricles. "Ptger4−/− mice: associated with increased fibrosis, reduced EF and dilated cardiomyopathy." (PMID 36314066, 2022). "Indeed, metformin signature also negatively correlates with the doxorubicin induced cardiotoxicity (SCC = −0.073, FDR = 4.83E‐15) and Ptger4‐/‐ model of dilated cardiomyopathy (SCC = −0.054, FDR = 4.19E‐8)." (PMID 32529766, 2020).
lung adenocarcinoma (3 papers, 2022 to 2024). A carcinoma that arises from the lung and is characterized by the presence of malignant glandular epithelial cells. "In human lung adenocarcinoma (TCGA, PanCancer Atlas, 510 patients/samples), CD274 mRNA levels are positively correlated with COX1 (PTGS1), EP2 (PTGER2), EP4 (PTGER4), and DP (PTGDR) with Spearman’s or Pearson’s coefficients over 0.3 and the coefficient of determination (R2) over 0.1." (PMID 37370700, 2023).
allergic asthma (2 papers, 2016 to 2025). A asthma with a basis in a pathological type I hypersensitivity reaction. "In a model of allergic asthma, an increase in airway levels of PGE2 was associated with a rise in MVL; this change was absent in Ptger2−/− and Ptger4−/−mice." (PMID 26639895, 2016).
endometrial adenocarcinomas (2 papers, 2011 to 2015). "Our in vivo data suggest that endometrial adenocarcinoma growth is regulated by the PTGER4 pathway and hypoxia." (PMID 21589857, 2011). "Here, we show suppression of PTGER1 and PTGER3 and elevated expression of PTGES2 and PTGER4 in endometrial adenocarcinomas compared with normal endometrium." (PMID 21589857, 2011). "Here we investigated (a) the expression profile of the PGE synthase enzymes (PTGES, PTGES-2, PTGES-3) and PGE receptors (PTGER1–4) in endometrial adenocarcinomas compared with normal endometrium and (b) the role of PTGER4 in endometrial tumorigenesis in vivo." (PMID 21589857, 2011). "We show that inoculation of nude mice with Ishikawa endometrial adenocarcinoma cells stably expressing PTGER4 promotes formation of tumour xenografts which grow at a significantly faster rate compared with tumours arising from WT control cells." (PMID 21589857, 2011). "We found elevated expression of PTGES2 (P<0.01) and PTGER4 (P<0.01) in all grades of endometrial adenocarcinomas compared with pooled normal endometrium." (PMID 21589857, 2011). "In endometrial adenocarcinomas, PTGER4 is localised to the neoplastic epithelial compartment." (PMID 21589857, 2011). "Using WT Ishikawa endometrial adenocarcinoma cells and Ishikawa cells stably transfected with the full length PTGER4 cDNA (PTGER4 cells) xenografted in the dorsal flanks of nude mice, we show that PTGER4 rapidly and significantly enhances tumour growth rate." (PMID 21589857, 2011). "To investigate the mechanism and crosstalk whereby PTGER4 and hypoxia could regulate cellular proliferation in endometrial adenocarcinoma cells, we used our PTGER4 stable cell line in vitro." (PMID 21589857, 2011). "Furthermore our data propose a novel molecular mechanism whereby PGE2 biosynthesis, driven by elevated expression of PTGS2 in endometrial adenocarcinoma cells, and hypoxia synergise to increase PTGER4 expression and subsequently enhance cell proliferation and tumour growth." (PMID 21589857, 2011). "We found elevated expression of PTGES2 and PTGER4 and suppression of PTGER1 and PTGER3 in endometrial adenocarcinomas compared with normal endometrium." (PMID 21589857, 2011).
renal carcinoma (2 papers, 2024). A carcinoma arising from the epithelium of the renal parenchyma or the renal pelvis. "Furthermore, PTGER4 is closely associated with alterations in the cell cycle and the stimulation of senescence in renal cancer cells." (PMID 38605343, 2024). "Therefore, we chose PTGER4, a gene closely associated with metabolism in SeMRM, to study the effect of its expression on renal cancer cell proliferation, invasion and migration in vitro and in vivo." (PMID 38605343, 2024). "Subsequent experiments showed that the increase in PTGER4 suppressed the proliferation of renal cancer cell lines, and similar results were observed in both cell types." (PMID 38605343, 2024). "Simultaneously, PTGER4 was probed both in vitro and vivo in the experimental mode, and the impact of its expression level on lipid metabolism and the cell cycle of renal cancer cells was found." (PMID 38605343, 2024). "The renal cancer cells in the group with high PTGER4 were mostly in the G0/G1 phase, while the low PTGER4 were mostly in the S/G2 phase." (PMID 38605343, 2024). "Increased PTGER4 reduced the content of neutral lipid droplets in renal cancer cells." (PMID 38605343, 2024). "To study whether the difference in PTGER4 expression can affect the lipid content of renal cancer cell lines, we performed BODIPY staining on the cells in both the experimental unit and the control unit." (PMID 38605343, 2024).
rheumatic disease (2 papers, 2019 to 2021). "Importantly, we did not observe significantly increased EP4 expression levels in Th17 cells from patients with RA, a rheumatic disease without an association with PTGER4 gene variants." (PMID 31253169, 2019).
sarcoidosis (2 papers, 2020 to 2023). Sarcoidosis is a multisystemic disorder of unknown cause characterized by the formation of immune granulomas in involved organs. "According to Gini score calculated from gene expression values, we examined the top-6 most important AA metabolism-related genes (including PLA2G6, PLA2G7, AKR1C1, AKR1C3, LTA4H, and PTGER4) in sarcoidosis, whose expression showed a positive correlation with sarcoidosis samples." (PMID 33097805, 2020).
spondyloarthritis (2 papers, 2019 to 2020). "Polymorphisms (rs10440635 and rs76523431) in PTGER4 loci were associated with increased PTGER4 gene expression in synovial biopsy samples from patients with spondyloarthritis but also the susceptibility and severity of AS." (PMID 30381825, 2019).
tuberculosis (2 papers, 2023 to 2025). A chronic, recurrent infection caused by the bacterium Mycobacterium tuberculosis. "In another ongoing study we participated in, 9% of the pleural effusion samples from tuberculosis patients showed positive methylation of PTGER4 and/or SHOX2 genes." (PMID 40777114, 2025).
aortic valve disease (1 paper, 2024). "Additionally, AS from LVH demonstrates upregulated anti-inflammatory COX receptor-related genes PTGER2 and PTGER4, and LOX-derived LT receptor-related gene CYSLTR2, but downregulated TBXAS1 and ALOX5, suggesting different mechanisms causing aortic valve disease and aortic calcification." (PMID 39062733, 2024).
autism (1 paper, 2014). Persistent deficits in social interaction and communication and interaction as well as a markedly restricted repertoire of activity and interest as well as repetitive patterns of behavior. "The region of maternal association on chromosome 5 falls between the PTGER4 and DAB2 genes, in a region previously implicated in autism and ADHD." (PMID 24571439, 2014).
cardia cancer (1 paper, 2016). A malignant neoplasm involving the cardia of stomach. "Similarly, PLCE1 rs2274223 and PTGER4 and PRKAA1 rs13361707 were used to predict the risk of cardia cancer in populations with a hereditary background, who faced a greater than 3-fold higher risk (P < 0.05*)." (PMID 27127881, 2016). "Also those with a hereditary background including the risk alleles PLCE1 rs2274223 and PTGER4/PRKAA1 rs13361707 were 3 times more susceptible to cardia cancer than those without." (PMID 27127881, 2016).
channelopathy (1 paper, 2023). Channelopathies are a group of diseases caused by the dysfunction of ion channel subunits or their interacting proteins. "Other interesting gene variants in AS about Piezo2 channelopathy are the prostaglandin EP4 receptor (EP4)-coding PTGER4 gene and the endoplasmic reticulum aminopeptidase-coding ERAP1 gene." (PMID 37895134, 2023).
dwarfism (1 paper, 2022). "These genes were mainly involved in bone resorption (e.g., PTGER4), bone mineralization (e.g., BMP6), and dwarfism (e.g., GDF6 and PTDSS1)." (PMID 34893856, 2022).
endometrial tumour (1 paper, 2011). "To elucidate a role for the PGE2-PTGER4-cAMP pathway in endometrial tumour growth, we stably transfected Ishikawa endometrial epithelial cells with the full length PTGER4 cDNA transcript." (PMID 21589857, 2011). "Taken together, our data for the first time highlight a role for PTGER4 in endometrial tumour development." (PMID 21589857, 2011). "We investigated the impact of PTGER4 on endometrial tumour development in vivo using a nude mouse model." (PMID 21589857, 2011). "To determine a role for PTGER4 in endometrial tumour development, we stably transfected the full length PTGER4 cDNA transcript into Ishikawa endometrial epithelial cells." (PMID 21589857, 2011). "It is plausible that similar mechanisms may regulate PTGER4 signalling in vivo to promote endometrial tumour cell growth." (PMID 21589857, 2011). "The suppression of these receptors and augmentation of PTGER4, strongly suggest that PGE2, produced via PTGS and PTGES2, is a driver of endometrial tumour development via the activation of PTGER4 and initiation of cAMP signalling." (PMID 21589857, 2011).